SMURF1 (SMAD specific E3 ubiquitin protein ligase 1)
Diseases named in the same sentence as SMURF1 in open-access papers (continued):
Sharing a sentence is not in itself a finding about the gene and the disease.
tumor (59 papers, 2012 to 2026). "In GC, highly expressed SMURF1 has been observed in tumor tissues and cell lines, which was associated to malignant phenotypes and decreased survival." (PMID 36825281, 2023). "Our work advances the understanding of the function of Smurf1 and Smurf2 in tumor biology and provides new potential diagnostic and drug targets for Shh-MB." (PMID 37537194, 2023). "High Smurf1 expression was associated with larger tumor size, poorer histological type and lymph node metastasis." (PMID 30631050, 2019). "Smurf1 interacts with a tumor suppressor, RASSF1A (Ras association domain family member 1), to enhance the ubiquitination of RhoA; therefore, RhoA levels are decreased and tumorigenesis is suppressed." (PMID 31248165, 2019). "Because there are only 37 cases of non-tumor liver samples that have linked BMI values in the TCGA data set, the median SMURF1 expression level was used as the cutoff to plot BMI values." (PMID 30566427, 2018). "Amplification of several members of the NEDD4-like E3 ligases, including SMURF1/2, is reported to be associated with tumour progression." (PMID 22724073, 2012). "Moreover, Smurf1 expression levels were shown to be positively associated with more advanced tumor-node-metastasis (TNM) stage of GC, and inversely correlated with patient survival." (PMID 30116722, 2018). "In conclusion, our study provides the first evidence for negative regulation of the pVHL-HIF pathway by USP9X through the novel pVHL E3 ligase Smurf1, which induces degradation of pVHL and its unstable mutants to promote progression of pVHL associated neoplasms." (PMID 27517496, 2016). "Tumor cells utilize the highly expressed Smurf1 to link the growth signal to mTOR, providing an evidence for continuously coping with external pressures." (PMID 40958774, 2025). "Although SMURF1 displays either oncogenic or tumor-suppressing characteristics depending on the cellular context, the majority of studies showed that SMURF1 plays an oncogenic role." (PMID 39331402, 2025). "Smurf1 plays a bidirectional regulation of the mTOR‐TFEB axis in the balance between tumor growth and stress‐induced cell homostasis." (PMID 40958774, 2025). "For example, SMURF1 has been shown to act as a tumor promoter through ubiquitination modification and/or degradation of tumor suppressor proteins." (PMID 37454373, 2023). "FaDu cells treated with miR-194-5p inhibitors and SMURF1-siRNAs demonstrated notable reductions in the tumor-forming properties of animal models." (PMID 37568787, 2023). "The pro-tumor property of SMURF1 was attributed to suppress the expression of DAB2IP and subsequently enhances activation of the PI3K/AKT pathway." (PMID 36825281, 2023). "In HCC cells, SMURF1 shows a tumor suppressive role and positively regulates the phagophore nucleation by enhancing the PI3KC3 activity via stabilization of UVRAG." (PMID 36918822, 2023). "The tumor size of the SMURF1 or NRF2 deletion groups was smaller than that of the control group, but the tumor size of the NRF2 deletion group was smaller than that of the SMURF1 deletion group." (PMID 37316499, 2023). "Collectively, these data suggest that Smurf1 and Smurf2 play an important role in driving Shh signaling-mediated tumor growth, possibly through the ubiquitin E3 ligase activity." (PMID 37537194, 2023). "The expression of SMURF1 was noted to be reduced in the tumor tissues derived from miR-125a-transfected CT26 cells." (PMID 37568787, 2023). "Here, we reported a tumor-suppressive role for Smurf1 and Smurf2 during Shh-MB progression, which was proven by the following evidence." (PMID 37537194, 2023). "The aberrantly expressed SMAD‐specific E3 ubiquitin protein ligase 1 (Smurf1) has been reported to play a pivotal role in multiple tumor types." (PMID 34614303, 2022).
tumor (continued). "Human Smurf1 (Smad ubiquitin regulatory factor 1) is a tumor promoter by ubiquitination modification and/or degradation of tumor-suppressing proteins, and it is principally expressed in the nervous system, bone, lung, reproductive organs, and other tissues." (PMID 35034538, 2022). "Casein kinase 2-interacting protein-1 (CKIP-1, also known as PLEKHO1) inhibits tumor growth by causing inactivation of serine/threonine kinases and self-degradation of Smurf1, which is a potential oncogenic target in various tumor cells." (PMID 35449571, 2022). "As one of the more active E3 ubiquitin ligases, Smurf1 has been reported to be involved in tumor progression." (PMID 35233069, 2022). "Smad ubiquitination regulatory factor 1 (Smurf1) is a HECT-type E3 ubiquitin ligase that acts as a tumor enhancer or suppressor in various biological processes." (PMID 33794905, 2021). "In tumor cells, the ubiquitination and subsequent degradation of Smurf1 changes its modulation for TGF-β-independent mechanism and thus cellular processes." (PMID 33718111, 2020). "According to recent studies, SMURF1 plays dual roles in tumors, acting as both a tumor promoter and suppressor." (PMID 33377649, 2020). "Smurf1 is highly expressed in numerous tumor tissues and several experiments have demonstrated the metastasis-promoting role of Smurf1 in human cancer cells." (PMID 33114139, 2020). "Specifically, as a tumor promoter, Smurf1/2, which is remarkably highly expressed in tumor cells, leads to poor prognosis." (PMID 33718111, 2020). "Previous studies demonstrate that miR-577 is a well-recognized tumor suppressor and it negatively regulates a lot of oncogenes and oncogenic pathways, including Sphk2, Smurf1, Rab14, Rab25, LRP6, β-catenin, Wnt2b, and so on." (PMID 33069244, 2020). "When combined with mTOR inhibitor rapamycin, SMURF1 silencing resulted in the increased tumor sensitivity to rapamycin leading to significant inhibition of tumor growth in an orthotopic GB model." (PMID 32984016, 2020). "In conclusion, the present results demonstrated that the overexpression of miR‐125a can repress the malignant phenotype of CRC cells in vitro and inhibit tumor growth in xenograft mouse models in vivo, with Smurf1 as a potential and functional target." (PMID 31141316, 2019). "In vivo, miR‐125a overexpression downregulated the expression of Ki67 and Smurf1, thus leading to a marked reduction in tumor growth." (PMID 31141316, 2019). "The existence of similar Smurf1-regulated tumor promoting mechanism was also observed in clear cell renal cell carcinoma (ccRCC) cells." (PMID 30116722, 2018). "The currently available data stipulate that Smurf1 acts as an oncogene, whereas Smurf2 operates both as a tumor suppressor and a tumor promoting molecule, depending on the tumor stage, type, molecular binding partners, and other still unidentified factors." (PMID 30116722, 2018). "Subsequently, Vial's group showed that Smurf1 expression is required for lamellipodia formation, tumor cell plasticity, and motility through the regulation of peripheral RhoA/ROCK/MLC2 signaling." (PMID 30116722, 2018). "Another gene related to adhesion, integrin inhibition and suppression of focal adhesion formation, SMURF1, was upregulated in liprin-α1 knockdown cells, which is also likely to have anti-tumor activity." (PMID 30005669, 2018). "Moreover, circCAPG encodes a polypeptide which increases tumor growth by blocking the binding of the serine/threonine kinase (STK38) and SMAD-specific E3 ubiquitin protein Ligase 1 (SMURF1) in TNBC." (PMID 41081939, 2025). "It has been shown that SMURF1 is a potential tumor promoting factor." (PMID 40342823, 2025).
tumor (continued). "Intriguingly, circCAPG can be translated into a polypeptide named CAPG-171aa which promotes tumor growh by disrupting the binding of serine/threonine kinase 38 (STK38) to SMAD-specific E3 ubiquitin protein ligase 1 (SMURF1) and thereby preventing MEKK2 ubiquitination and proteasomal degradation." (PMID 37408008, 2023). "Taken together, these findings highlight a tumor-suppressive role for Smurf1 and Smurf2 in Shh-MB." (PMID 37537194, 2023). "This study underscored that Smurf1 promoted tumor cell survival by upregulating p62 liquid droplet formation and degradation and might serve as a potential target for cancer therapy." (PMID 36810259, 2023). "Among the Smurf1 substrates found so far, RhoA, belonging to the Rho GTPases family, is involved in regulating cell polarity, cell migration, cell differentiation, and tumour development." (PMID 36579844, 2023). "Notably, negative correlations between GAB1 and Smurf1 or Smurf2 were observed, confirming the downregulated expression of Smurf1 and Smurf2 in Shh-MB and supporting a tumor-suppressive role of Smurf1 and Smurf2 during Shh-MB progression." (PMID 37537194, 2023). "Therefore, the role and regulation of Smurf1 or Smurf2 are emerging critical topics in tumor biology research." (PMID 37537194, 2023). "Previous reports have shown that Smurf1 is degraded mainly through the ubiquitin–proteasome system, but it remains unclear whether Smurf1 is degraded by autophagy in tumor cells." (PMID 34614303, 2022). "More notably, existing evidence suggests that Smurf1 promotes tumor progression through PTEN." (PMID 35034538, 2022). "Because PI3K/Akt signaling is related to tumor cell progression, whether autophagy degrades overexpressed Smurf1 to inhibit the tumor growth is worth further investigation." (PMID 34614303, 2022). "Whether Smurf1 inhibition regulates tumor stemness to re-sensitive TMZ requires further investigation." (PMID 36291166, 2022). "Further studies are required to validate whether inhibition of Smurf1 through the activation of autophagy is effective for tumor treatment." (PMID 34614303, 2022). "How to degrade overexpressed Smurf1 in tumor cells and to maintain homeostasis remain largely unknown." (PMID 34614303, 2022). "Whether E3 ubiquitin ligase Smurf1 interacts with p62 and is degraded by autophagy in tumor cells remains elusive." (PMID 34614303, 2022). "In summary, our study shows that autophagy degrades overexpressed Smurf1 in GB cells, and the enhancement of autophagy in high Smurf1 expression tumor cells could be a potential antitumor approach." (PMID 34614303, 2022). "Importantly, the mechanistic biomarkers including JWA, p-p38, GATA-1, NEDD4, and SMURF1 were correspondingly changed in tumor tissues." (PMID 33875644, 2021). "Nevertheless, other studies have shown that Smurf1 can inhibit tumor activity." (PMID 34531986, 2021). "For example, phosphorylation of Smurf1 on Thr145 is not important for DAB2IP binding, Smurf1-mediated degradation of DAB2IP, or modulation of Smad1, but it does cause Smurf1 abundance and structural stability, which further increases the degradation of DAB2IP, resulting in tumor progression." (PMID 33718111, 2020). "Therefore, unveiling the mechanisms of how CKIP-1 stimulating autoubiquitination of Smurf1 and thereby affecting its activity in tumor cells is a subject worthy of further researching." (PMID 33718111, 2020). "Phosphorylation of Smurf1 plays a dual role in tumor development." (PMID 33718111, 2020). "Considering that miR‐125a negatively influenced Smurf1 expression, it was hypothesized that miR‐125a could inhibit tumor cell proliferation and migration." (PMID 31141316, 2019). "Because of its specificity for RhoA, Smurf1 also plays a role in tumor migration and invasion." (PMID 31248165, 2019). "Finally, consistent with the in vitro results, it was identified that miR‐125a downregulated Smurf1 in a mouse tumor xenograft model." (PMID 31141316, 2019).
tumor (continued). "Next, we investigated the role of SMURF1 in tumor growth by xeno-graft mice models." (PMID 29433542, 2018). "Furthermore, the authors reported that Smurf1-knockdown in GC cells markedly inhibits tumor growth and liver metastasis in vivo." (PMID 30116722, 2018). "According to the SMURF1 mRNA expression levels retrieved from the gene expression profile (GEO: GSE14520), we separated non-tumor liver tissue samples into the high SMURF1 expression (top 25%) group (n = 61) and the low SMURF1 expression (bottom 25%) group (n = 59)." (PMID 30566427, 2018). "Importantly, activation of the Par6/Smurf1/RhoA pathway which leads to RhoA degradation has been shown to be required for maintaining tumor cell motility and epicardial cell invasion." (PMID 27223264, 2016). "Because differentiation and loss of clonogenicity occurred only after downregulation of SMURF1 and reactivation of BMP pathway, these results support our hypothesis that SMURF1 inhibition of BMP signaling supports the maintenance of CSC-like tumor population." (PMID 25471937, 2014). "Finally, we analyzed the relationship of Smurf1 and Smurf 2 with immune cells in tumor tissues." (PMID 37291499, 2023). "Moreover, the cell proliferation marker Ki67 was significantly decreased in the SMURF1 and NRF2-deficient tumor compared with the control group, and the Ki67 was significantly decreased in the NRF2-deficient tumor compared with the SMURF1-deficient tumor cells." (PMID 37316499, 2023). "Therefore we set out to determine whether these tumor regulatory mechanisms mediated by Smurf1 are dependent on DAB2IP." (PMID 27036023, 2016). "In vivo, SMURF1 silencing restored METTL14 expression and attenuated PSMC5-driven tumor growth and lung metastasis." (PMID 42212325, 2026). "Although the same Zhang group reported previously small molecular inhibitors of SMURF1, such as A01 and A17, with inhibitory activity against SMURF1-mediated SMAD1/5 polyubiquitylation, these compounds had limited effects on tumor cell growth." (PMID 39331402, 2025). "Levels of SMURF1 and TGFBR2 were noted to be remarkably reduced in miR-17/20 mimics-transfected HepG2 cells, which potently enhanced their tumor-forming abilities." (PMID 37568787, 2023). "Significantly, TMZ suppressed the growth rate, size, and weight of tumors in LN229-shSmurf1 compared to in LN229-shScramble, suggesting that the combination of Smurf1 inhibition and TMZ treatment synthetically inhibited tumor growth." (PMID 36291166, 2022). "Other studies demonstrated that Smurf1 regulates multiple substrates, including UVRAG, Kindlin-2, ER-alpha, and p120-catenin, to promote tumor progression in different cancers." (PMID 36291166, 2022). "Without degradation by Smurf1, DAB2IP negatively regulates downstream pathways, but Smurf1 enhances Ras-MAPK and NF-kB oncogenic pathways by targeting DAB2IP, which bolsters tumor cell proliferation, survival, and migration." (PMID 33718111, 2020). "Mechanistically, they linked the Smurf1 pro-oncogenic activities with the ability of Smurf1 to negatively regulate the expression of DAB2IP, a GTPase-activating protein (GAP) and a suggested tumor suppressor." (PMID 30116722, 2018). "The interactions of SMURF1 and SMURF2 with TGF-β/BMP pathway regulators indicate that these genes may play dual roles in both tumor-suppressive and oncogenic mechanisms, depending on the cellular context." (PMID 41752056, 2026). "Understanding Smurf1's regulation in the mTOR‐TFEB axis, which balances tumor growth and stress‐induced cell homeostasis, may provide novel therapeutic targets for tumor progression and drug resistance." (PMID 40958774, 2025). "We identified the tumor-suppressing role of SMURF2 in LUAD, but whether SMURF1 has the same effect needs to be further studied." (PMID 37497010, 2023).
tumor (continued). "Autophagy induction via SMURF1-mediatd activation of UVRAG was shown to functionally result in autophagic degradation of oncoprotein EGFR and, consequently, suppress HCC cell proliferation and tumor growth." (PMID 36918822, 2023). "Accordingly, phosphorylation-resistant mutant of Smurf1 did not influence cell proliferation or apoptosis of the primary tumor." (PMID 35654587, 2022). "DAB2IP, also known as a tumor suppressor in ccRCC, has been reported to be epigenetically repressed by EZH2-mediated methylation of lysine 27 in histone H3 (H3K27me3), and also be degraded by SMURF1-mediated ubiquitin-proteasome regulation." (PMID 35562342, 2022). "The MEFs from Smurf1+/+ mice and Smurf1−/− mice, as well as the mice model of subcutaneous GB, also confirmed the combination of Smurf1 inhibition and TMZ treatment further inhibited tumor growth." (PMID 36291166, 2022). "SMURF1 is HECT‐type E3 ubiquitin ligase and functions as tumor facilitator in diverse cancers." (PMID 32248648, 2020). "Smurf1, a HECT domain Ub ligase, targets active GTP-RhoA for ubiquitination at the specific cellular protrusion, which inhibits contractility and stress fiber formation, ultimately promoting tumor cell migration and invasion." (PMID 29080116, 2018). "In addition, the tumor suppressor RASSF1A prevents tumorigenesis via interacting with Smurf1 and promoting Smurf1-mediated ubiquitination of RhoA." (PMID 29080116, 2018). "Indeed, Rho degradation via the ubiquitin ligase Smurf1 locally impaired Rho/ROCK signaling and promoted mesenchymal motility, while Smurf1 inhibition induced amoeboid motility in tumor cells in subcutaneous xenografts." (PMID 23024796, 2012).